CFTR (CF transmembrane conductance regulator)
Diseases named in the same sentence as CFTR in open-access papers (continued):
Sharing a sentence is not in itself a finding about the gene and the disease.
pancreatic disease (23 papers, 2011 to 2025). "It is reported that NC_000007.13:g.117149147G>A induces pancreatic disease and CFTR-RD, and NC_000007.13:g.117251848C>T reduces the activity of the encoded CFTR protein by 10–15%." (PMID 34740355, 2021). "Immunoreactive trypsinogen levels reflect severity of pancreatic disease and pancreatic function, which in turn is associated with the severity of the CFTR gene defect." (PMID 31640630, 2019). "Although the association between CFTR genotypes and pancreatic disease is well characterized, the association between CFTR genotype and pulmonary phenotypes is less understood, perhaps due to variable fluctuations in lung function in CF patients." (PMID 28800122, 2017). "Together, these findings provide new understanding of the complexity of pancreatic disease related to CFTR-associated duct dysfunction." (PMID 25033378, 2014). "Our integrative approach revealed a new functional class of rare CFTR variants of clinical significance in pancreatic disease." (PMID 25033378, 2014). "Next comparing pancreatic disease in the CF ferret with our observations presented here in the CFTR−/− sheep, the most notable difference is the time scale, as the ferret pathology primarily appears at term and develops after birth." (PMID 39112965, 2024). "Here we use a sheep model of CF (CFTR−/−) to examine the evolution of pancreatic disease through gestation." (PMID 39112965, 2024). "By contrast, pancreatic disease was uniformly progressive in CFTR-F508del ferrets removed from modulators and similar to CFTR-KO and CFTR-G551D ferrets, suggesting that residual fCFTR-F508del activity was insufficient to slow pancreatic disease." (PMID 38646935, 2024). "We were encouraged by recent observations indicating that CFTR-deleted ferrets developed dramatic pancreatic disease that mimicked the human condition." (PMID 30305676, 2018). "Future studies that investigate how much CFTR chloride channel function is necessary for the correction of pancreatic disease would be a fundamental knowledge for the progression of CF pathogenesis." (PMID 30662403, 2018). "Similarly, CFTR-knockout ferrets, which mimic human lung and pancreatic disease, offer a promising model to study CFTR-related kidney damage." (PMID 40807208, 2025). "The complete rebound of pancreatic function in our patient, despite pre-existing severe EPI, suggests that early intervention with CFTR modulators might alter the natural course of pancreatic disease in CF, a concept previously thought unattainable." (PMID 39507496, 2024). "Similarly, in the CFTR−/− sheep model pancreatic disease with acinar and ductal dilation, mucus obstruction and fibrosis is evident by 80 days of gestation (147 days)." (PMID 39112965, 2024). "Of these proteins, CFTR seems to play a central role in pancreatic diseases." (PMID 36609875, 2023). "Ductal cell alkaline secretions, regulated by the cystic fibrosis transmembrane conductance regulator (CFTR), play an important role in the pathophysiology of pancreatic disorders, as impaired pancreatic secretions and CFTR dysfunction have been observed in different forms of CP." (PMID 36830970, 2023). "Thus, the CFTR-F508del ferret model may have utility for studying mechanisms of CFTR-F508del biosynthesis in vivo, disease pathogenesis, and for assessing therapeutics that target lung and pancreatic diseases." (PMID 38646935, 2024). "Intron 8 of the CFTR gene was studied by sequencing in chronic alcoholics diagnosed with pancreatic disease (group A), alcoholics without pancreatitis (group B), and blood donor volunteers who served as healthy controls (Group C)." (PMID 21845156, 2011). "While CF rats do not spontaneously develop lung or pancreatic disease during their first 6-weeks of life, they are a good model for investigating bone growth and its direct link to CFTR, without the presence of other disease manifestations such as airway disease." (PMID 30662403, 2018).
intestinal obstruction (22 papers, 2012 to 2024). Blockage of the normal flow of the intestinal contents within the bowel. "The combined pathophysiology of exposure to TPN and lipids, nothing per os condition encouraging biliary sludge, CFTR malfunction within biliary ducts, and intestinal obstruction are the primary causes of increased liver enzymes and cholestasis." (PMID 38893705, 2024). "Prior studies have demonstrated that both epithelial and smooth muscle CFTR loss contribute to the bowel obstruction phenotype in CF mice." (PMID 37568151, 2023). "Identification of MSRA as a modifier of MI provides new insight into the biologic mechanism of neonatal intestinal obstruction caused by loss of CFTR function." (PMID 22438829, 2012). "We studied newborn pigs with complete loss of CFTR by homozygous deletion of exon 10 (referred to as CFTR−/−) or severe loss of CFTR function by F508del knock-in mutations (CFTRΔF508/ΔF508) that consistently develop MI with a severe intestinal obstruction that would require surgery for survival." (PMID 38665380, 2024). "A commonly-used animal model in CF research is the Cftrtm1Unc Tg(FABP-hCFTR) mouse, which displays gut-specific expression of a human CFTR transgene in order to rescue the high rate of early mortality in Cftr-null mice associated with severe intestinal obstruction." (PMID 34799297, 2022). "For this reason, a loss of function of CFTR protein can lead to intestinal obstruction (called ileum meconium) as the earliest clinical phenotype of CF, and to intestinal complications in paediatric/adult age as a secondary site of CF manifestations (after the lung)." (PMID 23613805, 2013). "In both the human and mouse small intestine, CFTR is localized to goblet cells that produce MUC2; mouse models with defective CFTR develop a similar phenotype to the one of people with CF including bowel obstruction and bacterial overgrowth." (PMID 36117114, 2023). "The primary goal of the study was to assess the potential of the oral intestine-specific NHE3 inhibitor tenapanor for the prevention of intestinal obstruction in CFTR null mice." (PMID 36077390, 2022). "In the optimized mouse model utilized in this study, the CFTR gene was disrupted globally, whereas the lethal problem of intestinal obstruction was corrected by expressing human CFTR in the intestines." (PMID 34271850, 2021). "Autopsies performed on F508del and CFTR KO rats revealed intestinal obstruction, which usually occurred at the level of the cecum with a dilated appearance of the small intestine." (PMID 31942562, 2019). "Slc26a9 deletion strongly reduces the survival of CFTR KO mice, particularly in the weaning phase, where the mice die of intestinal obstruction." (PMID 24965066, 2015). "CFTR knock-out ferrets and pigs have been shown to develop intestinal obstruction that is anatomically and temporally equivalent to that observed in humans; however, the phenotype is highly penetrant in these animals (75% and 100%, respectively)." (PMID 22438829, 2012). "For those symptoms that are presented in mouse models, such as the intestinal obstruction phenotype that is observed in CFTR−/− mice, the presentation differs from what is observed in humans." (PMID 23151353, 2012). "A mouse carrying the G542X nonsense mutation in the CFTR locus was generated by CRISPR nucleases showing common manifestations of CF determined by the absence of CFTR ion channel, such as intestinal obstruction and reduced growth." (PMID 32486152, 2020). "CFTR-/- sheep developed a severe disease similar to CF including pancreatic fibrosis, intestinal obstruction and the absence of vas deferens." (PMID 32486152, 2020). "These mice have decreased CFTR expression and a lack of CFTR function in the airways and intestine; they have low survival rates due to intestinal obstruction." (PMID 30662403, 2018).
intestinal obstruction (continued). "Previous studies by our group have shown that restoration of the cystic fibrosis transmembrane conductance regulator (CFTR) in the intestinal epithelium prevents intestinal obstruction but does not improve growth." (PMID 28384265, 2017). "Absence of functional CFTR on the enterocyte BBM leads to intestinal obstruction while increased CFTR on the enterocyte BBM leads to excessive fluid secretion and diarrhea." (PMID 23644890, 2013).
malnutrition (22 papers, 2015 to 2025). Inadequate nutrition resulting from poor diet, malabsorption, or abnormal nutrient distribution. "The pathogenesismay be related to malnutrition, deficiencies of essential fatty acids, carnitine,choline, oxidative stress, and insulin resistance, and not only to a CFTR gene." (PMID 31241693, 2019). "Aberrant metabolite levels have been reported, but whether CFTR loss itself or secondary abnormalities (infection, inflammation, malnutrition, and various treatments) drive metabolic defects is uncertain." (PMID 38743489, 2024). "The new highly effective CFTR modulators, therefore, open up new perspectives in CF, which has traditionally been characterized by malnutrition, poor growth and low weight, and nowadays also by excessive body weight, as reported in the literature." (PMID 40806881, 2025). "Malnutrition in CF now includes an increasing prevalence of overweight and obesity, particularly in those receiving CF transmembrane conductance regulator (CFTR) modulator therapy (CFTRm)." (PMID 40071679, 2025). "The metabolic effect of ETI through the restoration of CFTR is therefore exerted with different degrees in people with CF, with the highest responses seen in patients with underweight and malnutrition secondary to CF." (PMID 37330504, 2023). "In our cohort, the tendency towards improved DEXA test results following one-year reflect improvement in factors contributing to osteopenia including CFTR dysfunction, malabsorption of fat-soluble vitamin D, and malnutrition." (PMID 36266606, 2022). "However, since the implementation of neonatal screening, the use of high-calorie diets, management in accredited units, and the introduction of CFTR modulators, there has been a progressive reduction in malnutrition and an improvement in albumin levels." (PMID 39599636, 2024). "Steatosis, present in approximately 60% of patients, especially those with malnutrition, excessive fat consumption, impaired phospholipid metabolism, and essential fatty acid deficiency, is not directly linked to the CFTR defect." (PMID 38473009, 2024). "Paneth cell markers were also downregulated in EED chips compared with healthy chips in control medium (for example, MT2A, CFTR and MT1H were suppressed by ~2–2.5-fold, respectively), but were differentially regulated when chips were exposed to nutritional deficiency." (PMID 35739419, 2022). "While other mechanisms related to CFTR dysfunction including altered transit time, intestinal pH, and intestinal fat content underlie malnutrition, fecal bile acid loss appears to occur independent of these processes." (PMID 34578785, 2021). "Cystic Fibrosis Transmembrane Regulator (CFTR) modulator therapy commenced shortly after the present study was conducted, hence no data were reported on the association of malnutrition risk and the specific therapy." (PMID 33291524, 2020). "Intestinal alterations due to CFTR dysfunction may result in malnutrition with consistent respiratory muscle weakness and comprised innate lung defences." (PMID 26484665, 2015). "However, the start of treatment with CFTR protein modulators has led to a significant increase in BMI values, and an increase in the prevalence of overweight and obesity has even been observed in this population with a classical tendency towards malnutrition." (PMID 39339703, 2024). "We consider that further clinical studies are needed to help us to understand the role of CFTR modulators and timing of treatment initiation in preventing EPI and malnutrition in children with CF and thus in improving the quality of life and possible the survival rate." (PMID 36678791, 2023). "Genetic susceptibility due to genetic mutations particularly in SPINK1, CFTR, CTRC, and CLDN2/MORC4 genes is the most important factor and not malnutrition or dietary toxins for idiopathic CP suggesting the term ‘tropical pancreatitis’ is a misnomer." (PMID 29868209, 2016).
pneumonia (20 papers, 2010 to 2025). An acute, acute and chronic, or chronic inflammation focally or diffusely affecting the lung parenchyma, caused by an infection in one or both of the lungs (by bacteria, viruses, fungi, or mycoplasma.). "Pseudomonas aeruginosa secretes the bacterial toxin Cif, which inhibits USP10, leading to decrease USP10-mediated deubiquitination of CFTR and increase CFTR degradation in lysosomes, causing the weaker mucociliary clearance and the harder removal of pathogens to cure pneumonia." (PMID 38322269, 2024). "Recently we demonstrated a strong association in African American children with pneumonia between lung injury and a polymorphic (TG)mTn site located close to the splice junction between intron 8 and exon 9 of the cystic fibrosis transmembrane conductance regulator (CFTR) gene." (PMID 27596159, 2016). "Together these results indicate that CFTR plays a role in ARDS in children with pneumonia and predict that genetic variants that affect the expression of functional CFTR, including variants in proteins involved in the regulation of CFTR mRNA splicing, will be associated with ARDS." (PMID 27596159, 2016). "The decrease in CFTR activity could increase risk for pneumonia through several mechanisms." (PMID 41180002, 2025). "Among mice infected with the highly mucoid Sp CHB756, all CFTR–/– and WT mice developed severe pneumonia, marked by diffuse inflammatory infiltrates with many neutrophils 24 hour post-infection." (PMID 26469863, 2015). "Both wild-type mice and CF transmembrane conductance regulator (CFTR) knockout mice exhibit a female disadvantage in mortality from pneumonia due to a mucoid CF clinical isolate, the P. aeruginosa strain PA508 (PA508), and female wild-type mice mount a stronger inflammatory response in their lungs." (PMID 21118573, 2010). "Possible change of CFTR expression in the lung under high fever may induce or aggravate pneumonia." (PMID 26515683, 2015). "To determine whether the Ess system was required for virulence in the murine pneumonia model, we infected cystic fibrosis transmembrane conductance regulator (CFTR) knockout mice intra-nasally with either of RN6390, COL and SA113 or the cognate ess deletion strains." (PMID 25040609, 2014). "Similarly, high frequency of MEFV variants in Middle Easterners and Ashkenazi Jews have been proposed to protect against Yersinia pestis infections, CFTR and GJB2 variants against diarrhea, and CYP21A2 variants have been hypothesized to decrease mortality from pneumonia." (PMID 40162233, 2025). "We then applied this framework to several additional experimental models: lysogeny broth (LB), a mouse pneumonia model, synthetic sputum medium (SCFM2), and the in vitro CFTR ΔF508 CFBE41o– mutant polarized airway epithelial cell model." (PMID 31937646, 2020). "Under these conditions, therapeutics that can restore CFTR function or CBF can restore MCC and prevent microbial colonization consequently decreasing the incidence of pneumonia in People living with HIV." (PMID 26528246, 2015). "This is not surprising, given that both wild-type mice and CFTR knockout mice exhibit a marked female disadvantage in mortality from PA508 pneumonia and female wild-type mice mount a stronger inflammatory response in their lungs." (PMID 21118573, 2010). "Defective mucociliary clearance and function of the cystic fibrosis transmembrane conductance regulator (CFTR) in airway epithelium and submucosal glands plays a crucial role in the lung colonization by the opportunistic Gram-negative bacteria Pseudomonas aeruginosa causing pneumonia." (PMID 34326452, 2021). "In summary, multivariable analysis adjusted for the (TG)mTn site in CFTR and for demographic and clinical factors, has identified an association between polymorphisms in CELF2 and risk of developing ARDS in both African American and non-Hispanic Caucasian children with pneumonia." (PMID 27596159, 2016).
prostate carcinoma (20 papers, 2013 to 2025). A carcinoma that arises from epithelial cells of the prostate gland. "The data which follow suggest that the occurrence of prostate cancer associated with defective CFTR may be related to a decline in ARSB and may be responsive to treatment by rhARSB." (PMID 40362587, 2025). "Reports have indicated that CFTR may act as a tumor suppressor in prostate cancers associated with bisphenol-A (BPA) exposure." (PMID 40362587, 2025). "Moreover, caveolin-1 is also associated with c-Myc in prostate cancer and KD of CFTR lead to increased inflammation and caveolin-1 levels." (PMID 35500936, 2022). "The V470 allele can reduce the activity of the CFTR protein chloride channel, which might help to reduce the disease damage and decrease the rate of diarrhea, primary sclerosing cholangitis, and prostate cancer." (PMID 34276759, 2021). "Cisplatin increases CFTR expression and enhances chemoresistance and the cell viability of prostate cancer tissues compared with chemo-sensitive prostate cancer tissues in vivo and LNCaP cells in vitro." (PMID 35205604, 2022). "The CFTR IVS8-5T polymorphism, associated with low CFTR expression levels, was also reported to be protective against prostate cancer in the Chinese population." (PMID 32365523, 2020). "Other studies found a high frequency (64%) of CFTR methylation in prostate cancers with a high malignancy score and high proliferation levels, i.e., poorer prognosis." (PMID 32365523, 2020). "In prostate cancer, urokinase plasminogen activator (uPA) has been suggested as key signal for CFTR-induced anti-cancer responses to proliferation and invasion." (PMID 32182826, 2020). "Cystic fibrosis transmembrane conductance regulator (CFTR), which is a tumor suppressor, regulates progression of prostate cancer by suppressing uPA through miR-193b." (PMID 31262974, 2019). "Our previous studies have demonstrated that CFTR acts as a tumor/EMT suppressor, which is shown to be downregulated and associated with poor prognosis in prostate cancer, breast cancer, colon cancer and lung cancer." (PMID 28978008, 2017). "Additionally, knockdown of CFTR increased the sensitivity of prostate cancer cells to cisplatin treatment." (PMID 33614474, 2020). "It should be noted that our previous studies have also observed a link between CFTR and uPAR in prostate cancer and non-small cell lung cancer, however, CFTR was found to suppress uPAR in the cancer tissues in contrast to a positive correlation with uPAR observed in the present study." (PMID 28978008, 2017). "CFTR is also frequently downregulated in breast and prostate cancers." (PMID 24386311, 2013). "In contrast, prostate cancer tissues exhibited frequent deep deletions in ABCG2, ABCG1, ABCC4, ABCA2, ABCC2, ABCC7/CFTR, and ABCC9." (PMID 40641097, 2025). "We not only analysed the expression levels of CFTR in HT-29 cells, HIF-1α in HEK-293T cells, GAPDH in liver tissue of mouse, and serum AFP in HCC patients, but also the glycosylation changes in the sera of prostate cancer patients, in combination with the optimised fixation method." (PMID 31040299, 2019).